CD53 (CD53 molecule)
Diseases named in the same sentence as CD53 in open-access papers (continued):
Sharing a sentence is not in itself a finding about the gene and the disease.
nasal polyps (1 paper, 2022). "Among these genes, PLEK was reported to be involved in CRSwNP but not correlated with M2 macrophages while AIF1, CD53 and LAPTM5 were related to M2 macrophages but not explored in nasal polyps." (PMID 36466903, 2022).
nonalcoholic steatohepatitis (1 paper, 2023). "In vivo, CD53 deletion in nonalcoholic steatohepatitis diet-fed mice blocked peripheral adipose accumulation and adipose inflammation, insulin tolerance, and liver lipid accumulation." (PMID 36581203, 2023).
periodontitis (1 paper, 2024). An acute or chronic inflammatory process that affects the tissues that surround and support the teeth. "In addition, correlation analysis showed that CD53, CYBB, and PLEK were significantly positively linked with activated CD4+T cells in the immune microenvironment of peri‐implantitis, making them effective biomarkers to differentiate it from periodontitis." (PMID 38780047, 2024).
tumor (83 papers, 1980 to 2025). "CD53 antigen interaction protects against the apoptotic response caused by serum deprivation and contributes to cell survival in the poorly vascularized region of the tumor mass." (PMID 34234827, 2021). "Since CD53 expression is associated with only the PKHhi and PKHlo cell fractions of tumors and exhibits an intermediate stem cell frequency (1/16097), this strongly suggests an association with regenerative functions within a tumor." (PMID 27140846, 2016). "The upregulation or downregulation of CD53 expression in various diseases, including cancer, can therefore potentially affect the tumor microenvironment and immune response." (PMID 40923331, 2025). "We also identified new potential trogocytic markers such as CD4 and CD53 on the trogocytic tumor samples." (PMID 40440354, 2025). "CD53 was highly expressed in both tumor and normal tissues, while FCER1G and TYROBP showed higher expression in tumors compared to normal tissues." (PMID 38971817, 2024). "Our results show that NCFs and their coexpressed genes, including SPI1, HCK, VAV1, CD53, and ITGB2, are significantly associated with tumor-infiltrating immune cells, especially with immunosuppressive macrophages." (PMID 34708124, 2021). "The tetraspanin “web” regulates protein trafficking and signalling, as well as cell-to-cell adhesion and migration; therefore, tetraspanins (including CD53) influence both T and B cell proliferation, as well as leukocyte migration into tumour microenvironment." (PMID 35201443, 2021). "These coexpression factors (SASH3 and CD53) can be used to classify tumor purity phenotypes and to predict clinical outcomes." (PMID 34234827, 2021). "Thereby, these results suggest CD53 to be a putative marker for tumor initiating/regenerative potential." (PMID 27140846, 2016). "Our study is possibly the first to identify and validate a strong correlation of CD53 with tumor regenerative capabilities." (PMID 27140846, 2016). "The TPX2 signature was tumor cell autonomous and predictive of DMFS only in those patients who were ER+ at diagnosis, and was distinct from a CD53 network that was associated with ER-negative stromal components." (PMID 22693453, 2012). "CD53 has been identified as a tumor initiation marker in cancer stem cells." (PMID 40548122, 2025). "Among genes showing high positivity in both intra- and peri-tumour TILs, CD53 appears to be a good candidate as prognostic marker for cancer patients, since it plays a key role in anti-tumour immunity, as already reported for other members of the tetraspanin superfamily." (PMID 35201443, 2021). "It has also been reported that CD53 is linked to tumor necrosis factor-α (TNF-α) expression by genome-wide association analysis, which may change the tumor immunogenic microenvironment and then affect the immune response." (PMID 34856991, 2021). "CD53 is a member of the tetraspanin family, which is a group of cell surface proteins that participate in cell adhesion, motility, signal transduction, immune cell activation, tumor growth, and metastasis." (PMID 34856991, 2021). "CD53 is also involved in tumour antigen uptake by dendritic cells (DCs), the most professional antigen-presenting cells that activate and direct T cells toward the tumour, thereby promoting tumour immune-surveillance." (PMID 35201443, 2021). "We finally identified SASH3 and CD53 as tumor purity-related prognostic factors." (PMID 34234827, 2021). "Furthermore, they proposed that CD53 ligation shifts NK cells towards a more proliferative phenotype, based on observed reductions in the degranulation responses of NK cells towards tumor cells, and impaired cytokine production." (PMID 32440787, 2020). "CD53-mediated anti-tumor immunity could be a factor that promotes the response to ICB treatment." (PMID 37492578, 2023).
tumor (continued). "Moreover, research has shown that the expression of CD53 is very high in radioresistant tumor cells, making this an even more attractive prospect as it may provide a new option in difficult to treat malignancies." (PMID 32440787, 2020). "Several important genes emerged in this study that are overexpressed in BA versus WA patients in both tumor and TAS, including PIK3CA, mTOR and CD53." (PMID 34316327, 2021). "The results suggested that CD4, CD53, EVI2b, PLEK, and SASH3 correlated with tumor purity, immune score, CD8+ T cells, and clinical phenotypes." (PMID 34234827, 2021). "Five coexpressed genes (CD4, CD53, EVI2B, PLEK, and SASH3) were identified as tumor purity coexpressed genes that negatively correlated with tumor purity." (PMID 34234827, 2021). "The RNA transcriptomes for all the tumor samples showed the three markers GPR56, CD53 and CD59a are expressed as mRNA, together with low expression of CD25." (PMID 30962539, 2019). "Indeed, the WGCNA of TCGA-LUAD cohort revealed that patients with this tumor phenotype had down-regulated an extensive gene network led by SASH3 and including IKZF1, IL10RA, CD53 and SNX20, all involved in immune activation." (PMID 39107857, 2024). "Genes upregulated in both tumor and TAS of BA PCa patients as compared to WA included cell cycle markers CD19, CD2, CD53 and CD80, interferon response factor 8 (IRF8), phosphoinositide 3-kinase (PIK3CA), mechanistic target of rapamycin (mTOR), and metastasis-associated protein S100A4." (PMID 34316327, 2021). "Such gene modules often correlate with biological functions; one such specific association was the enrichment of CD53 expression in CSCs, functional validation indicated CD53 to be a tumor-initiating cell- rather than quiescent CSC-marker." (PMID 27140846, 2016). "However, the CD53 antibody evoked a weak redirected inhibition of cytotoxicity towards the Fc-receptor+ NK sensitive tumor target P388D1, indicating that CD53 transduce signals that may negatively affect NK cytotoxicity." (PMID 24832104, 2014).
cancer (49 papers, 2004 to 2026). A tumor composed of atypical neoplastic, often pleomorphic cells that invade other tissues. "From the MSigDB Cancer Neighbourhood Ontology, we found that the GM-enriched binding windows were in proximity to cancer-associated genes, CD53, VAV1, INPP5D, STAT6, HLA-C, etc." (PMID 25522020, 2014). "Similarly, NKG7, ARHGAP9, C1QA, and CD53 were accurately predicted in 15/28 datasets (R = 0.38–0.46 for the various cancer types)." (PMID 32747659, 2020). "Moreover, other genes from diverse functional groups appeared in our analysis, such as signal transducers promoting cancer growth (CD53, RAB33A, GNA11, CANX, OCRL, GIPC1, and SOS1), microtubule formation (KIF21B) and cell migration (ASAP2)." (PMID 29535628, 2018).
bacterial infections (1 paper, 2018). "For example, a small case study of individuals deficient in the leukocyte-restricted tetraspanin CD53 revealed that they were affected by recurrent bacterial infections." (PMID 30072994, 2018).
CD53 also shares sentences with these, for which no sentence is quoted: colorectal cancer (5 papers); osteosarcoma (5); acute myeloid leukaemia (4); Ewing sarcoma (4); cancers of the liver (3); infection (3); infectious disease (3); pancreatic cancer (3); glioblastoma (2); mesothelioma (2); metastatic cancers (2); psoriasis (2); renal cell carcinoma (2); acute lymphoblastic leukemia (1); adenocarcinoma (1); allergic asthma (1); Arthritis (1); B-cell non-Hodgkin lymphoma (1); breast tumor (1); cerebral malaria (1); cervical cancer (1); cholestasis (1); chronic lymphocytic leukemia (1); Cognitive impairment (1); colon carcinoma (1); contact dermatitis (1); cytomegalovirus infection (1); diffuse large B-cell lymphoma (1); embryonal carcinoma (1); embryonal tumors (1).
A further 33 diseases each share a sentence with CD53 in 1 paper.